MLKL (mixed lineage kinase domain like pseudokinase)
Diseases named in the same sentence as MLKL in open-access papers (continued):
Sharing a sentence is not in itself a finding about the gene and the disease.
infection (continued). "MLKL phosphorylation-mediated necroptosis has been extensively studied in higher mammals mainly in humans and mice to combat with pathogen infection." (PMID 40085533, 2025). "First, parasite replication was measured in naïve WT, RIPK3−/−, and MLKL−/− BMDM following infection with mCherry Type II T. gondii (ME49) tachyzoites." (PMID 41055414, 2025). "To further determine the necrotic nature of a fusogenic and non-fusogenic OV-mediated death, we analyzed the expression and phosphorylation of the necroptosis mediators, RIPK1, RIPK3, and MLKL, over the time course of infection by western blot analysis." (PMID 40896365, 2025). "We also conducted a time course experiment to evaluate the expression of MLKL during the first 6 h of infection." (PMID 40490945, 2025). "RIPK1 degradation with R1-ICR-3 also reduced MLKL phosphorylation during HSV-1(ICP6mut) infection in both HS68 and HFFs." (PMID 39345610, 2024). "During IAV (Influenza A virus) infection, the cell death regulator MLKL facilitates potassium ion efflux, partially activating the NLRP3 inflammasome." (PMID 39735183, 2024). "PPV infection induced a significant increase in p-RIPK3 and p-MLKL 24 h post-infection when apoptosis was inhibited; however, the expression and cleavage of Caspase-8 was not changed." (PMID 39614405, 2024). "We also found that in PTCs with apoptosis inhibited, MLKL was mainly translocated near the cytomembrane in the PPV-infected PTCs at 72 h post-infection, while MLKL was distributed in the cytoplasm of the mock-infected PTCs." (PMID 39614405, 2024). "In contrast, SN50 reduced p65 nuclear translocation, SOD2 expression, and phosphorylated MLKL in N2aC24 cells after IAV/WSN infection." (PMID 39194237, 2024). "Here, we observed a trend toward increased phospho-MLKL in response to several of the strains at both 24 hours and 48 hours post-infection." (PMID 37928185, 2023). "A range of diverse non-necroptotic functions have been attributed to RIPK3, including a central role in cytokine and chemokine initiated immune control of infection, and RIPK3-dependent but MLKL-independent mechanisms have been implicated in immune defense." (PMID 36792599, 2023). "This demonstrates the critical role played by RIPK3 in phosphorylation of MLKL in human macrophages both constitutively and in response to infection and a smaller role for RIPK1 in response to infection." (PMID 37000865, 2023). "HCMV merlin strain infection degrades mixed lineage kinase domain-like protein (MLKL) which is a key regulator of cellular necroptosis." (PMID 37424781, 2023). "In the mouse L929 cell line, mainly T3DK and jin-1 induce p-MLKL expression at 30 h post infection, while for wt-R124 p-MLKL expression is increased slightly above the background level." (PMID 36768641, 2023). "Here authors show, by introducing a mutation into mouse MLKL representing a frequently occurring human single nucleotide polymorphism, that MLKL mutations could critically alter the inflammatory response and the clearance of Salmonella from organs upon infection." (PMID 37770424, 2023). "We ascertained similar findings for MLKL phosphorylation, including the significant additive effect in M. tb-infected, 666-15-treated MDMs at 90 min post infection." (PMID 37000865, 2023). "At the earlier stages of infection, MLKL-mediated necroptosis drives inflammasome activation, contributing to the maturation of IL-1β." (PMID 36852999, 2023). "We probed cell lysates for phosphorylated RIPK1, RIPK3 and MLKL by Western blot over a time course from 15–90 min post-infection." (PMID 37000865, 2023). "We also examined the impact of MLKL activation on the infection of these cells by Escherichia coli, a bacterium that mainly grows extracellularly but can also adhere to mammalian cells and be phagocytized by them." (PMID 34999730, 2022).
infection (continued). "In both 24h and 72h, expression of all the molecular biomarkers of necroptosis like MLKL, RIP1 and RIP3 was increased post infection with pathogenic L. interrogans." (PMID 35392072, 2022). "VACV E3LΔ83N infection of IFN-treated L929 cells leads to phosphorylation of MLKL that is inhibitable by GSK872." (PMID 35203445, 2022). "Knockdown of RIPK1, RIPK3, or MLKL in the background of infection with either RVA NCDV or DS-1 suppressed the expression of RVA proteins and titers." (PMID 34668777, 2022). "On the other hand, p-MLKL appears much earlier in infection in Hpse-KO cells, suggesting that this enhanced initial sensitivity is important in the marked difference in the subsequent host cell response." (PMID 33621216, 2021). "Next, the RIPK3 and phosphorylation of MLKL definitely increased in the lungs of STING-/- mice during early infection compared to the control mice." (PMID 34135886, 2021). "In our study increased phosphorylation of RIPK1, RIPK3, and MKLK in ZIKV-infected astrocytes was detected early in the infection but only RIPK3 and MLKL phosphorylation remained throughout the infection and cell death." (PMID 33796483, 2021). "Upon infection, deletion of MLKL in OTUB1LPC-KO mice significantly reduced ALT and LDH levels as compared to OTUB1LPC-KO illustrating that necroptosis aggravated liver damage in the absence of OTUB1." (PMID 33712742, 2021). "Consistent with the significant difference in the infection phenotype between the WT and MLKL-/- mice, the level of LDH release and the numbers of dead macrophages were also decreased in MLKL-/- mice compared to WT mice." (PMID 34135886, 2021). "Western blot analysis showed that the phosphorylation of RIPK3 and MLKL was increased by PRV GD-WH infection in PK-15 cells at 12 and 24 hpi." (PMID 34149651, 2021). "After oral infection, MLKL−/− mice succumb to infection, similar to WT mice, whereas RIPK3−/− mice showed improved survival." (PMID 33526566, 2021). "MVA-infection resulted in a time-dependent increase in MLKL phosphorylation in Hoxb8 and primary macrophages." (PMID 34711816, 2021). "The therapeutic potential of MLKL as a druggable target in infectious disease is highly nuanced and will require careful tailoring to the pathogen and infection site/stage in question." (PMID 34071602, 2021). "Both infection with Lm and stimulation with TNF significantly increased numbers of p-MLKL+ cells and the amount of p-MLKL per cell in OTUB1-deficient HepG2 cells as compared to OTUB1-sufficient HepG2 cells." (PMID 33712742, 2021). "Infection with HCMV strain AD169, which lacks a functional pUL36 protein, sensitized cells to necroptosis, in accord with the observed increase in MLKL protein upon infection with viruses deficient in functional pUL36." (PMID 32690704, 2020). "Here, we used a proteomic screen to identify human proteins targeted for destruction by HCMV, finding that the key necroptosis mediator MLKL is degraded throughout infection." (PMID 32690704, 2020). "In order to determine if VZV-infection prevented the phosphorylation of MLKL only within infected cells, dual immunofluorescence staining for VZV antigen and pMLKL was performed." (PMID 32649716, 2020). "According to these results, we concluded that ΔsopB infection increased LS174T cell necroptosis via upregulating MLKL phosphorylation." (PMID 31024858, 2019). "We found ΔsopB infection increased goblet cell necroptosis in cecum via upregulating MLKL phosphorylation." (PMID 31024858, 2019). "Collectively, these results indicated that ΔsopB infection promotes cell necroptosis via upregulating MLKL phosphorylation." (PMID 31024858, 2019). "Deletion the final executor of necroptosis MLKL abolished the increased bacterial translocation and severity to inflammation following ΔsopB infection." (PMID 31024858, 2019). "Consistently, MLKL deletion also ameliorated the inflammatory cytokines production in cecum following ΔsopB infection." (PMID 31024858, 2019).
infection (continued). "Following ΔsopB infection, MLKL−/− mice had decreased bacterial burdens in liver and spleen when compared to WT mice." (PMID 31024858, 2019). "Confocal imaging of uninfected and KPn infected neutrophils at 3hrs post-infection showed a strong phospho-MLKL signal on the plasma membrane of infected neutrophils which was similar to that observed with the positive control cells." (PMID 30273394, 2018). "Compared with WT mice, the AB-PAS staining mucins were dramatically reduced in MLKL−/− mice after infection." (PMID 29456533, 2018). "Exhilaratingly, we observed higher Salmonella burdens MLKL−/− epithelium at the acute stage of infection." (PMID 29456533, 2018). "Evidence has shown that MLKL-mediated necroptosis participates in many inflammatory diseases and is sufficient to protect the host against pathogens infection." (PMID 29456533, 2018). "As expected, following infection, the expression of claudin 3 was dramatically reduced in MLKL−/− epithelium." (PMID 29456533, 2018). "Both WT and mutant virus triggered MLKL phosphorylation (p-MLKL) as early as 6 h after infection, 4 h before cells became permeable." (PMID 30050136, 2018). "Here co-immunoprecipitation experiments demonstrate that a RIPK3- and MLKL-containing complex forms following dl922-947 infection and that MLKL phosphorylation (and hence activation) is evident upon caspase inhibition." (PMID 29238045, 2017). "To explore further, we performed RIPK3 co-immunoprecipitation and demonstrated an interaction between RIPK3 and MLKL following dl922-947 infection as well as an interaction between RIPK3 and adenovirus proteins." (PMID 29238045, 2017). "Following dl922-947 infection, we saw re-localisation of MLKL from the nucleus to the cell membrane, which is required for MLKL-induced necrosis." (PMID 29238045, 2017). "Consistent with our earlier observation, loss of NleF alone did not suppress ΔespL-induced necroptosis, since macrophage lysis following ΔnleF/espL infection remains sensitive to GSK’872 inhibition (Fig. EV5C), and MLKL phosphorylation upon ΔespL or ΔnleF/espL infection was identical (Fig. EV5D)." (PMID 40128366, 2025). "Our imaging data also indicated an accumulation of MLKL near the nucleus at 4 h post‐infection." (PMID 40490945, 2025). "Protein-level validation showed that the activation of key cell death markers, including Caspase-3, GSDMD, and MLKL, significantly increased as the infection progressed, with their dynamic changes correlating strongly with the expression pattern of viral proteins." (PMID 40076601, 2025). "Although the calculated fold changes for RIPK1 and RIPK3 phosphorylation were rather low and subject to high inter-experimental variation over the time course of infection, trends point toward an increased expression and phosphorylation of MLKL in rVSV-infected A549 and H1437 cells 16–24 hpi." (PMID 40896365, 2025). "We observed similar upregulation of MLKL in Optn ‒/‒ cells at 2 h and 4 h post‐infection." (PMID 40490945, 2025). "This suggested that PRV-GXLB-2013 ex vivo infection activated the NF-κB/MLKL signaling pathway." (PMID 40732040, 2025). "The results showed that caspase-3 was processed into its active form immediately after infection, and phosphorylation of RIPK3 and MLKL could be detected during the early infection." (PMID 40607949, 2025). "Indeed, ΔnleB/espL triggered reduced MLKL phosphorylation compared to ΔespL following infection in LPS-primed macrophages, and LDH release by ΔnleB/espL was no longer sensitive to GSK’872 inhibition." (PMID 40128366, 2025). "Moreover, in this study, we also highlight the necroptotic role of MLKL, which gets activated during the later stages of the infection leading to death of oligodendrocytes." (PMID 40490945, 2025). "The diverse non‐necroptotic functions of MLKL, which may be upregulated in response to infection, also warrant deeper exploration." (PMID 40490945, 2025).
infection (continued). "Additionally, in accordance with the established role of caspase‐8 in inhibiting necroptosis treatment with Z‐IETD‐FMK led to a slight increase in levels of phosphorylated MLKL during hCoV‐OC43 infection." (PMID 40810650, 2025). "Finally, we observed that MLKL contributes to TB pathology in high-dose infection of mice prone to formation of necrotic tuberculous lesions." (PMID 40950000, 2025). "However, phosphorylation of MLKL were markedly prevented in prion-infected cells after IAV/WSN infection, although other cell death markers were similarly increased between prion-uninfected and prion-infected cells." (PMID 39194237, 2024). "The results showed that the levels of p-RIPK3 and p-MLKL were significantly increased in the ZBP1 overexpression PTCs comparing with the vector control transfected cells (Vec) during PPV infection, while the expression levels of RIPK3, MLKL, and Caspase-8 did not significantly change." (PMID 39614405, 2024). "Additionally, confocal microscopy revealed a translocation of MLKL from the cytoplasm to the cell membrane at 72 h of PPV infection." (PMID 39614405, 2024). "In addition, neutralizing antibody to IL-1β reduced the cell viability of N2aC24L1-3 cells in a dose-dependent manner and increased phosphorylated MLKL in N2aC24L1-3 cells after IAV/WSN infection." (PMID 39194237, 2024). "Accordingly, infection or cellular stressors can lead to cell death by the combinatory crosstalk of pyroptotic, apoptotic, and necroptotic molecules (like ZBP1, RIPK1, RIPK3, CASP1, CASP8, and NLRP3, MLKL, and GSMDs) to effectively control pathogenic invasion." (PMID 38590437, 2024). "Quantification of the levels of twenty-six cytokines and chemokines in the lungs of WT and MLKL-deficient mice showed that mice lacking essential necroptotic signaling components responded similarly to WT animals upon infection." (PMID 38286985, 2024). "Targeting MLKL to endosomes seems to promote intracellular trafficking of bacteria, such as Listeria monocytogenes and Yersinia enterocolitica, to lysosomes to control infection." (PMID 37373257, 2023). "However, longer term inhibition of RIPK3/MLKL (72h post-infection) has previously been shown to extend cell viability by inhibiting necroptosis, coinciding with increased control of M. tb growth." (PMID 37000865, 2023). "To understand if necroptosis plays role in acute LCMV infection and disease, we infected WT, RIPK3-deficient (Ripk3−/−) or MLKL-deficient (Mlkl−/−) mice with a low dose LCMV Armstrong, an acute variant of the virus, and analyzed the immune response at day 8 post infection." (PMID 36792599, 2023). "Additionally, a thorough comparison of infection phenotypes across RIPK3 and MLKL-deficient mice is essential in all future studies attempting to attribute clinical outcomes to RIPK3 versus necroptosis." (PMID 36792599, 2023). "To determine and compare the effect of RIPK3 or MLKL-deficiency during late stages of LCMV docile infection, we measured the virals loads in the lung, liver, spleen, kidney and brain at 8, 35 and 100 days post infection." (PMID 36792599, 2023). "We evaluated the interactions of increased chemo-cytokines present in serum 72h post infection with L. interrogans from our previous study with the major necroptotic markers MLKL, RIP3 and RIP1 elevated in the spleen at 72h post infection in the present study through STRING proteome analysis." (PMID 35392072, 2022). "But, in RIP3-/- mice or in MLKL-/- mice, IL-17B had little infection to the plasma IL-6 and TNF-α." (PMID 36046722, 2022). "Furthermore, at 24h and 72h, expression of the necroptosis molecular biomarkers p-MLKL, p-RIP1 and p-RIP3 was increased post infection with pathogenic L. interrogans." (PMID 35392072, 2022). "Activation of TLR/TNF signaling during infection, combined with multiple expressions of apoptosis‐regulatory proteins, could also promote necroptosis indicating the phosphorylation of MLKL during BMDM infection." (PMID 34977874, 2021).
infection (continued). "Mice lacking both GSDMD and MLKL (pyroptosis/necroptosis) were similarly susceptible to lethal infection as Gsdmd−/− mice." (PMID 34154417, 2021). "Similarly, siRNA‐mediated knockdown of RIPK1 or RIPK3 in HT29 cells infected with ΔospD3 decreased levels of phosphorylated MLKL and cytotoxicity to the levels observed in WT infection." (PMID 32657447, 2020). "Moreover, we observed a raised protein level of both MLKL and p-MLKL in lung tissues of severe patients dying from human infection with H7N9 virus." (PMID 31080811, 2019). "Whether the increased RIPK1, RIPK3 and MLKL activation marks a typical necroptotic, lytic event during infection or if KPn utilizes the necroptosis machinery to modulate cellular functions in its favor, or a combination of both, requires further investigation." (PMID 30273394, 2018). "Finally, the number of alveolar macrophages detected in the BALF of infected MLKL KO mice 18h post-infection was significantly higher than wild type controls." (PMID 26659062, 2015). "However, further studies are needed to determine whether similar MLKL‐mediated mechanisms are at play in these other infections." (PMID 40490945, 2025). "To determine if RIPK1 mediates MLKL phosphorylation in ZBP1-deficient astrocytes following infection, we treated ZBP1+/+ and ZBP1−/− derived astrocytes with the RIPK1 inhibitor, GSK963, during infection with the HSV-1(MacIntyre), HSV-1(F)-ICP6-RHIM Mut, and HSV-1(F) strains." (PMID 35549723, 2022). "However, the densitometrical analysis of three independent experiments could only confirm a trend of activated MLKL due to induced phosphorylation in super-infected cells, whereas an induction of apoptosis upon IV infection could be verified." (PMID 33333815, 2020). "However, we were unable to detect any MLKL phosphorylation following dl922-947 infection." (PMID 29238045, 2017). "Infection with 103 TCID50 of PRV-GXLB-2013 resulted in significantly elevated levels of TNF-α, IL-1β, IL-6, IL-8, and MLKL in brain tissues, serum, and C8-D1A cells, compared to the control group (p < 0.01)." (PMID 40732040, 2025). "We observed that caspase-8 was inhibited throughout the infection, and the necroptosis pathway was also suppressed due to the inhibition of phosphorylation and activation of RIPK1, RIPK3, and MLKL, mediated by the TNFα and NF-κB signaling pathways." (PMID 40607949, 2025). "The results showed that the levels of phosphorylated MLKL, RIPK1, and RIPK3, and cytotoxicity were higher in cells infected with ΔospD3 than in cells infected with WT Shigella, indicating that ΔospD3 infection triggers necroptosis." (PMID 40931196, 2025). "In EGFP-PrP23-51-transduced N2aC24 cells, p65 nuclear translocation was disturbed, SOD2 expression and phosphorylated MLKL were decreased, and cell viability was increased after IAV/WSN infection." (PMID 39194237, 2024). "We showed that IAV/WSN infection increased the levels of the apoptosis marker cleaved caspase-3, the autophagic cell death marker LC3-II, and the necroptosis marker phosphorylated MLKL in prion-uninfected cells." (PMID 39194237, 2024). "Activation markers of ZBP1-mediated necroptosis, including RIPK3 phosphorylation (pRIPK3) and MLKL phosphorylation (pMLKL), were attenuated in R1-ICR-3-treated HT29-hZBP1 cells during HSV-1(ICP6mut) infection." (PMID 39345610, 2024). "The results showed that the expression of p-RIPK1/RIPK1, p-RIPK3/RIPK3, and p-MLKL/MLKL was increased with H37Rv infection, while si-NR_003508 effectively reduced the expression of p-RIPK1/RIPK1, p-RIPK3/RIPK3, and p-MLKL/MLKL." (PMID 37175724, 2023). "During infection VV induces TNF production, driving RIPK3 activation and consequent MLKL induced necroptosis." (PMID 36175538, 2023). "Infection with RVA was shown to activate receptor-interacting protein kinase 1 (RIPK1), RIPK3, and mixed-lineage kinase domain-like protein (MLKL), in infected cells, contributing to the necroptosis of the cell." (PMID 37243249, 2023).